LINC02594 (long independently transcribed non-coding RNA 2594)
Gene: Long non-coding RNA gene on chromosome 17 (43,679,341 to 43,706,709, forward strand). Ensembl gene ENSG00000267440.
Diseases named in the same sentence as LINC02594 in open-access papers:
LINC02594 is named in the same sentence as 1 disease in open-access papers, as found by Europe PMC text mining. Sharing a sentence is not in itself a finding about the gene and the disease. The quoted sentences say what the papers report.
gastric cancer (1 paper, 2023). A primary or metastatic malignant neoplasm involving the stomach. "LINC02594, also known as CTC-501O10.1, exhibits up-regulation in the plasma of patients diagnosed with gastric cancer and thus holds potential as a biomarker for detecting this malignancy." (PMID 37837543, 2023).